MCEE (methylmalonyl-CoA epimerase)
Description:
Methylmalonyl-CoA epimerase involved in propionyl-CoA metabolism.
Synonyms: GLOD2; MCE; MMCE
Tractability: Small molecule: it has a high-quality binding pocket. PROTAC: its protein half-life has been measured.
Gene: Protein-coding gene on chromosome 2 (71,109,684 to 71,130,279, reverse strand). Ensembl gene ENSG00000124370.
Subcellular location: Mitochondrion
Subcellular location (Human Protein Atlas): Nucleoli
Pathways (Reactome):
Metabolism: Propionyl-CoA catabolism
Gene Ontology:
Molecular function: methylmalonyl-CoA epimerase activity; protein binding
Biological process: L-methylmalonyl-CoA metabolic process; succinyl-CoA biosynthetic process; short-chain fatty acid catabolic process
Cellular component: mitochondrion; mitochondrial matrix
Genetic constraint (gnomAD): Loss-of-function variants: 4 observed, 10.55 expected, observed/expected ratio (o/e) 0.38, 90% interval 0.19 to 0.87. The upper end of that interval is the gene's LOEUF score, 0.87, which puts it in group 3 of 6, group 1 being the genes least tolerant of losing a copy. Missense variants: 201 observed, 207.24 expected, observed/expected ratio (o/e) 0.97, 90% interval 0.86 to 1.09. Synonymous variants: 75 observed, 76.45 expected, observed/expected ratio (o/e) 0.98, 90% interval 0.81 to 1.19.
Gene-disease validity (ClinGen):
ClinGen rates the evidence that MCEE causes each of these diseases.
methylmalonic acidemia due to methylmalonyl-CoA epimerase deficiency (autosomal recessive): Definitive. Methylmalonic acidemia due to methylmalonyl-CoA epimerase deficiency is a rare inborn error of metabolism disease characterized by mild to moderate, persistent elevation of methylmalonic acid in plasma, urine and cerebrospinal fluid.
Homologues: Orthologues: chimpanzee MCEE (99% identical), macaque MCEE (95% identical), dog MCEE (84% identical), mouse Mcee (80% identical), pig MCEE (80% identical), rat Mcee (80% identical), guinea pig MCEE (77% identical), tropical clawed frog mcee (66% identical), Caenorhabditis elegans mce-1 (56% identical). Paralogues in human: GLOD5 (20% identical).
Diseases named in the same sentence as MCEE in open-access papers:
MCEE is named in the same sentence as 12 diseases in open-access papers, as found by Europe PMC text mining. Sharing a sentence is not in itself a finding about the gene and the disease. The quoted sentences say what the papers report.
methylmalonic acidemia (4 papers, 2018 to 2024). A genetically heterogenous inherited disorder characterized by abnormalities in the metabolism of lipids and proteins. "Methylmalonic acidemia is an organic acidemia caused by a deficiency of the mitochondrial enzyme MCM or its cofactor cyanocobalamin, or in rare cases by a deficient activity of methylmalonyl-CoA epimerase (MCE)." (PMID 38722242, 2024). "Isolated methylmalonic acidemia (MMA) is caused by complete or partial deficiency of the enzyme methylmalonyl-CoA mutase (mut0 or mut– enzymatic subtype), a defect of its cofactor adenosyl-cobalamin (cblA, cblB, or cblD-MMA), or deficiency of the enzyme methylmalonyl-CoA epimerase." (PMID 33453710, 2021).
Methylmalonic aciduria (3 papers, 2016 to 2022). Increased concentration of methylmalonic acid in the urine. "MCEE deficiency has been shown to lead to methylmalonic aciduria and central nervous system damage in humans." (PMID 35981005, 2022).
giardiasis (1 paper, 2023). An infection of the small intestine caused by the flagellated protozoan giardia lamblia. "On the other hand, galactose mutarotase, aminomethyl transferase, and methylmalonyl-CoA epimerase expression were similar during giardiasis and UPEC infection." (PMID 36675151, 2023).
Parkinson disease (1 paper, 2025). A progressive degenerative disorder of the central nervous system characterized by loss of dopamine producing neurons in the substantia nigra and the presence of Lewy bodies in the substantia nigra and locus coeruleus. "MCEE encodes methionine-ethionine carboxy-lyase, essential for sulfur metabolism, while MPHOSPH10 encodes M-phase phosphoprotein 10, implicated in ribosome biogenesis and associated with Parkinson’s disease." (PMID 39796173, 2025).
Sepsis (1 paper, 2022). Sepsis is defined as life-threatening organ dysfunction caused by a dysregulated host response to infection. "Meanwhile, methylmalonyl-CoA epimerase (MCE), an enzyme involved in odd-chain fatty acid catabolism, was significantly down-regulated in sepsis heart mitochondria." (PMID 34506367, 2022).
genetic disorders (1 paper, 2023). "Methylmalonyl-CoA epimerase deficiency shares a similar biochemical profile with other rare genetic disorders." (PMID 38034150, 2023).
metabolic disease (1 paper, 2023). A congenital disorder (due to inherited enzyme abnormality) or acquired (due to failure of a metabolically important organ) disorder resulting from an abnormal metabolic process. "A few cases of non-mitochondria-related variants were evaluated as probably having mitochondrial disorders, such as variants in MMACHC, MCEE, FOLR1 and G6PC genes, which were grouped as causative genes of metabolic diseases affecting multiple systems." (PMID 36918699, 2023).
MCEE also shares sentences with these, for which no sentence is quoted: asthma (1 paper); cancer (1); homocystinuria (1); infection (1); organic acidemia (1).